ZEB1 (zinc finger E-box binding homeobox 1)
Diseases named in the same sentence as ZEB1 in open-access papers (continued):
Sharing a sentence is not in itself a finding about the gene and the disease.
breast carcinoma (continued). "Interestingly, the paralogous factor PTPB3, which prevents the ZEB1 mRNA degradation by binding to its 3′UTRis, contributes to the EMT posttranscriptional regulation in breast cancer." (PMID 37176013, 2023). "Considering our previous findings that NETs increase gene expression of ZEB1 and CD44 in MCF7 breast cancer cells, we hypothesized that NETs could induce EMT activation through TF upregulation." (PMID 38201433, 2023). "We found a trend toward a higher expression of mesenchymal markers such as ZEB1, N-cadherin, and TWIST, and lower expression of epithelial marker E-cadherin in cells with lower palbociclib activity (IC50 > 3.5 μM) among 11 HR+ breast cancer cell lines." (PMID 38017459, 2023). "Depletion of Zeb1 inhibited PI3K/AKT activity and aerobic glycolysis, which may indicate that Zeb1 depletion is potential therapeutic strategy for breast cancer because it led to attenuate aerobic glycolysis and reprogrammed TAM polarization." (PMID 37491279, 2023). "Here, we describe key roles for ZEB1 during early EMT stages in enhancing ERα responses and suggest that the functional ZEB1-ERα interaction may modulate the tissue tropism of breast cancer metastases." (PMID 35440541, 2022). "For example, TBL1X promotes EMT of breast cancer cells by acting as a cofactor of ZEB1 to regulate the expression of CDH1, and the high expression of TBL1X contributes to metastasis of breast cancer and is correlated with the poor prognosis of patients with breast cancer." (PMID 35173544, 2022). "In addition, TP73-AS1 boosted cell proliferation, invasion, and migration, and functioned as a ceRNA with miR-200a to prevent binding of TFAM, dampening the TP73-AS1/miR-200a/ZEB1 and TP73-AS1/miRNA-125a-3p/ metadherin axis in breast cancer." (PMID 35614413, 2022). "In addition, we confirmed that there were positive correlations among CD163 (TAM marker) expression, ZEB1 expression and DNMT1 expression in breast cancer patient tissues." (PMID 36273188, 2022). "Moreover, the accumulation of lactate derived from cancer cells with ectopic Zeb1 was found to contribute to the M2-like polarization of TAMs in the TME and thus promote the malignant progression of breast cancer in vitro and in vivo." (PMID 35246504, 2022). "This process is often referred to as dedifferentiation, and has been reported in many cancers, including glioblastoma, intestinal tumors, melanoma, and also in breast cancer, where CSCs arise through an epithelial-mesenchymal transition (EMT)-like process facilitated by the ZEB1 promoter." (PMID 35597788, 2022). "For example, PD-L1 could be upregulated in ZEB1 and miR-200 dependent manners EMT-activated human breast cancer cells." (PMID 36090897, 2022). "Finally, to evaluate the clinical significance of our findings, we performed immunohistochemistry (IHC) staining of breast cancer tissue microarray slides (TMAs) using anti-CD163 (TAM marker), anti-ZEB1 and anti-DNMT1 antibodies." (PMID 36273188, 2022). "Ets1 activates the ZEB1 promoter and induces endogenous ZEB expression in breast cancer cells." (PMID 35451213, 2022). "In addition, it has been reported that in breast cancer, TGF-β enhances cancer stem cell plasticity by reducing the presence of H3K27me3 at the ZEB1 (zinc finger E box-binding homeobox 1) promoter site." (PMID 36135315, 2022). "Importantly, we demonstrated concomitantly high expression of Zeb1, LDHA, and MCT4 in breast cancer patients with an advanced TNM stage, highlighting that Zeb1-mediated dysregulation of aerobic glycolysis is functionally linked to breast tumor malignancy." (PMID 35246504, 2022). "In breast cancer progression is also involved circ-ROBO1 (has_circ_0124696), which promotes breast cancer-derived liver metastasis by sponging miR-217-5p, known to target Zeb1." (PMID 35626752, 2022). "Moreover, ZEB1 has been also reported to be phosphorylated by ATM at S585, which enhances its protein stability in breast cancer cells." (PMID 35601657, 2022).
breast carcinoma (continued). "Recently, ZEB1 was shown to interact with AP-1 factors FOSL1 and Jun as well as the Hippo pathway effector YAP to form a multimeric transactivation complex, which in turn activated tumor-promoting genes in breast cancer cells." (PMID 34708244, 2022). "Interestingly, an autocrine feedback loop is generated in tumor cells to enhance an inflammatory phenotype, since SNAIL and ZEB1/2 are able to activate IL6 expression in head and neck squamous carcinoma and breast cancer." (PMID 34459003, 2021). "Our studies have provided novel finding that B3GALT5 plays a role in facilitating lymph node and lung metastasis through β-catenin/ZEB1 pathway, suggesting B3GATL5 might be potential target for tackling BCSCs, cell proliferation, and EMT in breast cancer." (PMID 33413566, 2021). "Because DNAJB9 modulated the FBXO45-mediated negative regulation of ZEB1, we further investigated whether DNAJB9 and FBXO45 affect the metastasis of breast cancer." (PMID 33966034, 2021). "HAS2 was found to promote ZEB1-mediated EMT and metastasis in breast cancer." (PMID 32862195, 2021). "Having demonstrated the involvement of SNAI1, further studies must be carried out to dissect whether other EMT-TFs, such as SNAI2, ZEB1, or TWIST, are also involved in the regulation of the CMTM members in breast cancer cells." (PMID 33803139, 2021). "TNFα exhibits antitumor effects through activation of programmed cell death and migration and invasion of breast cancer cells through activation NF-κB-dependent EMT-inducing transcription factors (EMT-TFs) such as Twist1, Snail, Slug, and Zeb1/2 that drive inactivation of E-cadherin." (PMID 34220337, 2021). "Further epigenetic regulation of ZEB1 depends on the protein arginine methyltransferases PRMT1, which induce the EMT process in breast cancer cells by mediating the asymmetric dimethylation of arginine 3 of histone H4 (H4R3me2as) at the ZEB1 promoter and activating its transcription." (PMID 34943943, 2021). "In addition, OSM has been described to increase the Zeb1 protein levels in PDAC and breast cancer and Zeb2 in cervical cancer." (PMID 34361105, 2021). "In breast cancer cells, FOSL1 expression correlates with mesenchymal features and drives cancer stem cells and the regulation of EMT seems to happen through the direct binding of FRA-1 to promoters of EMT genes such as Tgfb1, Zeb1, and Zeb2." (PMID 34399888, 2021). "In summary, the ATM/ZEB1/USP7/CHK1, miR-200c/LINC02582/USP7/CHK1, USP7/PHF8, UCHL3/RAD51, USP52/ASF1A, and UCHL1/HIF-1 signaling axis are potential targets to improve the radiosensitivity of breast cancer." (PMID 34575114, 2021). "Among other findings, one of identified strongly connected components in the breast cancer interaction network contained the double-negative feedback loop between miRNAs from mir-200 family and ZEB1/ZEB2 genes." (PMID 33852600, 2021). "ZEB1/MYB is another reciprocal negative feedback circuit involved in the process of breast cancer development." (PMID 32014049, 2020). "The miR-221/ZEB1 activity is efficiently targeted upon MEK1 inhibitor (TAK-733) treatment and when combined with irradiation treatment, significant reduction in migration of breast cancer cells was shown." (PMID 33327491, 2020). "Furthermore, it has been found that IRF6 (target of TP63) is induced by the NOTCH signaling pathway, which plays vital roles in the development and progression of cancers through regulating ZEB1 expression and EMT pathway, in breast cancer and keratinocytes." (PMID 33156825, 2020). "The results presented here confirm that MEK1 inhibitor treatment combined with irradiation could significantly decrease the migratory potential of breast cancer cells including reduction in miR-221 and EMT (ZEB1) marker expression changes." (PMID 33327491, 2020).
breast carcinoma (continued). "The western blot and the band intensity analysis hinted that over-expression of TUSC8 down-regulated the expression of mesenchymal related markers (ZEB1, TWIST, SNAI1 and Vimentin) in breast cancer cell lines SK-BR-3 and MDA-MB-435 (p < 0.05, p < 0.01 respectively)." (PMID 32039833, 2020). "In addition, HNK-mediated STAT3 inactivation triggered the STAT3-mediated release of ZEB1 from the E-cadherin promoter, increasing E-cadherin expression and inhibiting EMT of breast cancer cells accordingly." (PMID 32014049, 2020). "Furthermore, we propose that CTGF is a versatile regulator in breast cancer and facilitates SPARC, LOX, ZEB1, VIM and FN1 expression changes." (PMID 33087801, 2020). "An innovative and interesting study found that luminal breast cancer cell lines exhibited only presence of H3K27me3 and the relative absence of 3K4me3 and H3K79me2 at the ZEB1 promoter." (PMID 32014049, 2020). "Hence, the miR-200/ZEB1 autoregulatory loop represents a central knot on which pro- and anti-EMT pathways converge, and in breast cancer cells an autocrine TGFβ/ZEB/miR-200 signaling network regulates plasticity between epithelial and mesenchymal states." (PMID 33260366, 2020). "Furthermore, a dose-dependent inhibition of ZEB1 protein levels was confirmed in MDA-MB-231 and SUM-159 breast cancer cells in response to treatment with 50–150 μM biochanin A." (PMID 32296027, 2020). "However, it has been demonstrated that EMT contributes to evasion of immune surveillance in breast cancer and that PD-L1 is upregulated in EMT-activated human breast cancer cells by a mechanism involving ZEB-1 and miR-200." (PMID 32650408, 2020). "Conversely, knock-down of TUSC8 up-regulated the expression of mesenchymal related markers (ZEB1, TWIST, SNAI1 and Vimentin), and down-regulated the expression of epithelial related marker (E-cadherin) in breast cancer cell lines MCF-7 and HCC1937 (p < 0.05, p < 0.01 respectively)." (PMID 32039833, 2020). "Mutual exclusivity data from the n = 1,105 breast cancer TCGA dataset revealed that PAPP-A has a significant tendency towards co-occurrence with mesenchymal markers Vimentin (VIM), SNAI1 (Snail), SNAI2 (Slug), Zeb1, Zeb2 and Twist1." (PMID 32792532, 2020). "Lastly, following previous findings, only ZEB1, but not other transcriptional factors, including Snail or Twist, conferred radioresistance to the breast cancer model MCF7, even without inducing EMT." (PMID 32266287, 2020). "For the first time, we revealed a negative correlation between ZEB1 expression and pCR in breast cancer patients receiving NAT." (PMID 30976202, 2019). "Positive staining for CAM6/CAM5/E-cad and E-cad/ZEB1 was detected in Her2+ER−PR− (Her2-positive, estrogen receptor–negative, and progesterone receptor-negative) breast cancers more frequently than in other tumors." (PMID 31331982, 2019). "Thus, in breast carcinoma, PRMT1 methylates ZEB1 promoter, which then induces EMT and therefore implies ZEB1 as a negative prognostic parameter." (PMID 31655611, 2019). "We report here elevated levels of EMT markers (vimentin and ZEB1/2) and reduced levels of EMT-regulating miR-200 (miR-200b and miR-200c) in ER-positive breast cancer cells, MCF-7, that were resistant to tamoxifen, in contrast with the naïve parental MCF-7 cells that were sensitive to tamoxifen." (PMID 31827114, 2019). "The function of PRMT1 in modulating EMT was suggested through the regulation of Zinc Finger E-Box Binding Homeobox 1 (ZEB1) in breast carcinoma and Twist Family BHLH Transcription Factor 1 (TWIST1) in non-small lung carcinoma." (PMID 31655611, 2019). "In breast carcinomas, expression of ZEB1 has been reported to occur in the stromal compartment of supposing to represent two populations of cells: EMT-transformed neoplastic cells and stromal fibroblastic cells undergoing activation of ZEB1." (PMID 29416615, 2018).
breast carcinoma (continued). "Most breast cancer cells that exhibit relatively high ZEB1 mRNA, failed to present detectable ZEB1 protein based on direct immunoblotting, or ChIP followed by immunoblotting (data not shown)." (PMID 29744893, 2018). "Therefore, by defining a mechanism for the regulation of ZEB2 independently of ZEB1, which is mediated by FOXP3 and miR-155, we have been able to analyse the specific contribution of ZEB2 in human breast cancer cells." (PMID 29963231, 2018). "As far as we know, no previous data exists on claudin in relation to vimentin, Zeb1 and Sip1 expression in breast cancers." (PMID 29482498, 2018). "ZEB1 is reported to upregulate VEGF expression and stimulate angiogenesis in breast cancer." (PMID 29416649, 2018). "For instance, the presence of a genetic variation in the non-coding sequence of ERBB2 generating a binding motif for the major inducer of epithelial-to-mesenchymal transition ZEB1 can potentially increase the aggressiveness and tumourigenic potential of HER2-positive breast cancer cells." (PMID 29559730, 2018). "Cells with high ZEB1 (and ZEB2) expression classified as basal‐B breast cancer cells." (PMID 29744893, 2018). "Furthermore, ZEB1 levels correlate with CHK1 protein levels and poor clinical outcome in human breast cancer." (PMID 28968963, 2017). "Transcription of the cluster is regulated by ZEB1 and HSF2 in breast cancer cell lines." (PMID 29141042, 2017). "In contrast, the expression of ZEB2 was generally low in breast cancer cells compared to THP‐1 cells, an acute myelogenous leukemia cell line with known ZEB2 function, and showed weaker correlation with IL6 and IL8 expression than that of ZEB1." (PMID 28618162, 2017). "One report showed that breast cancer cells with MDR displayed enhanced metastatic activity, and they overexpressed N-cadherin, vimentin and the EMT-inducing transcription factors Slug, Twist and ZEB1/2." (PMID 28934275, 2017). "Therefore, ZEB1 and ZEB2 have essentially similar functions in the regulation of inflammatory response gene expression, especially IL6 and IL8, in the basal‐type breast cancer cells." (PMID 28618162, 2017). "In conclusion, ZEB1 and ZEB2, through the induction of various cytokines, including IL‐6 and IL‐8, facilitate tumor growth both in autocrine and in paracrine manners in basal‐type breast cancer cells." (PMID 28618162, 2017). "Therefore, ZEB1 overexpression may provide a mechanistic link between the development of aggressive breast cancer and the loss of ER-α expression and may provide a method to elucidate the ontogeny of ER-α-negative and/or antiestrogen-resistant breast cancer." (PMID 28383555, 2017). "As model system, we first assessed ZEB1, CD44, and LKB1 colocalization in two different breast cancer cell lines, the epithelial, luminal A subtype (MCF‐7) and the mesenchymal, metastatic type (MDA‐MB‐231), well representing the patients’ cohort in terms of primary tumor characteristics." (PMID 28700115, 2017). "Methylation-specific PCR analysis further revealed that ZEB1 overexpression in two luminal (MCF-7 and ZR-75-1) breast cancer cell types enhanced DNA methylation of the ER-α promoter, whereas ZEB1 knockdown in two basal (MDA-MB-231 and SUM-159) breast cancer cell types reduced this methylation." (PMID 28383555, 2017). "In addition, epithelial–mesenchymal transition (EMT)-related genes SLUG, MMP9, ZEB1 and SNAIL were also elevated, while E-cadherin, an epithelial cell marker, were reciprocally decreased in all three breast cancer cell lines examined." (PMID 28703802, 2017).
breast carcinoma (continued). "For instance, in breast cancer, basal cells exhibit bivalent chromatin states, with both activating and repressive marks for a key EMT‐TF, ZEB1, but luminal cells only have repressive marks for ZEB1." (PMID 28548345, 2017). "Moreover, lumican decreased the expression levels of the mesenchymal markers slug/snail-2 zeb1, vimentin and fibronectin and the epithelial marker E-cadherin in MDA-MB-231 breast cancer cells." (PMID 28332606, 2017). "Furthermore, the expression profiles of ZEB1 and ZEB2 are inversely correlated with those of ESRPs in human breast cancer cell lines and tumor specimens." (PMID 28618162, 2017). "In addition, ZEB1 transcriptionally represses genes of the miR-200 family, and that GRHL2 up-regulates the expression of miR-200b/c family members in breast cancer cells." (PMID 29110737, 2017). "For example, lnc-ATB could upregulate ZEB1 and ZNF-217, and then induce EMT, leading to trastuzumab resistance and invasion-metastasis in breast cancer." (PMID 28086241, 2017). "The inhibition of ZEB1 to restore ER-α expression, in combination with methylation inhibitors and/or HDAC inhibitors, will represent a new strategy for overcoming antiestrogen resistance in breast cancer." (PMID 28383555, 2017). "In conclusion, we demonstrated that the negative feedback loop of miR-340 and ZEB1 participates the breast cancer progression." (PMID 27036021, 2016). "Survival analysis of breast cancer data sets demonstrated that irrespective of the subtype, tumours with high expression of ZEB1 and ‘common ZEB1/YAP target genes' displayed a significant shorter relapse-free and overall survival." (PMID 26876920, 2016). "Similar to the induction by estrogens, there were discrepancies in different cellular environments in breast cancer, with a correlation of AR and ZEB1 expressions being evident in ER-negative but not in ER-positive cells." (PMID 26797644, 2016). "The targets of the top luminal miRNAs were activators of EMT (ZEB1, ZEB2) and basal subtype transcription (IL-6, EGFR, STAT3), whereas the targets of the top basal miRNAs were involved in adipogenesis pathways and luminal breast cancer (ERBB2, ERBB3)." (PMID 27845906, 2016). "In addition to elevation of E-cadherin, downregulations of ZEB1, N-cadherin, and vimentin were found in AESN-treated MCF-7 breast cancer cells." (PMID 27136519, 2016). "ZEB1 and SIP1 have been found to repress primary transcript and mature miR-200 expression in mesenchymal types of breast cancer cells, suggesting a downregulation of miR-200 in TNBC cells through a potential double-negative feedback loop between ZEB1/SIP1 and the miR-200 family." (PMID 27484639, 2016). "Our data revealed that, among the classic EMT-associated transcription factors (Twist, Snail, Slug and ZEB1) we tested, only the expression of ZEB1 was found to be regulated by PRMT1, and the PRMT1-mediated activation of ZEB1 was crucial for initiation of EMT process in breast cancer cells." (PMID 26813495, 2016). "Similarly, in breast cancer and renal clear cell carcinoma under normoxia condition, HIF-1 increases ZEB1 expression and thus regulates EMT." (PMID 26882471, 2016). "Positive correlation between ZEB1 and VEGFA expression in breast cancer." (PMID 26882471, 2016). "Because of the negative effect on E-cadherin, the overexpression of ZEB1 results in tumor metastasis and predicts an unpleasant prognosis in a lot of cancers, especially breast cancer." (PMID 27036021, 2016). "Lastly, in radioresistant subpopulations of breast cancer cells induced by irradiation, ATM, a protein activated by KAT5 acetylation, is hyperactivated and mediates stabilization of ZEB1, another well known EMT inducer, in breast cancer and other types of solid tumours." (PMID 27581651, 2016). "Positive correlation between ZEB1 and CD31 expression in breast cancer." (PMID 26882471, 2016).